KCNQ2 (potassium voltage-gated channel subfamily Q member 2)
Diseases named in the same sentence as KCNQ2 in open-access papers (continued):
Sharing a sentence is not in itself a finding about the gene and the disease.
epilepsy (continued). "The antagonism of 5-HT6R improves the impaired LTP in chronic epileptic rats by regulating the KCNQ2/3-mediated M-currents, especially KCNQ2-mediated M-currents, and may serve as a promising candidate in the clinical treatment of epilepsy." (PMID 32425770, 2020). "In the present study, we investigated a series of cases with KCNQ2 mutation variants from patients with childhood nonlesional epilepsy." (PMID 31199083, 2019). "KCNQ2‐related epilepsy led to varied outcomes (from benign to severe) in our patients." (PMID 31199083, 2019). "However, it is effective at opening KCNQ2/3 channels and was clinically useful, mostly as an add-on therapy, in epilepsy." (PMID 31701029, 2019). "Caused primarily by sporadic, KCNQ2 loss-of-function mutations (as carriers tend not to reproduce), this disease is notable for severe developmental delays in addition to epilepsy." (PMID 31701029, 2019). "The percentages of KCNQ2‐associated epilepsy were not consistent but depended upon what kinds of patients were enrolled." (PMID 31199083, 2019). "We found KCNQ2 mutations in about 5% of nonlesional childhood epilepsy patients, and in about 13% of patients with neonatal seizure onset when they were younger than 2 months." (PMID 31199083, 2019). "KCNQ2 mutations accounted for 5% of all nonlesional pediatric epilepsy and 13% of patients with seizure onset before 2 months old." (PMID 31199083, 2019). "KCNQ2-related epilepsy is another example where a molecular diagnosis may influence the therapeutic choice." (PMID 28082152, 2018). "It suggests that CaM may regulate neuronal excitability by KCNQ2, and it could be a target of gene therapy in epilepsy." (PMID 30213136, 2018). "Indeed, KCNQ2 is targeted by a drug recently licenced for the treatment of epilepsy, retigabine, which is efficacious is sporadic epilepsy." (PMID 28334860, 2017). "This may suggest that, although CACNA1A contributes to epilepsy mutational load, the noise from other pathway-related genes (CHRNA4, KCNQ2, KCNQ3 and PLCB1) compromises this effect." (PMID 27984588, 2016). "This dramatic form of KCNQ2-related epilepsy, with very poor neurological outcome, was unexpected." (PMID 23692823, 2013). "This would be advantageous because KCNQ2/KCNQ3 channels have been the focus of extensive pharmacologic research in relation to epilepsy, and several compounds that act either as activators or inhibitors of the complex have already been identified and are in various stages of clinical investigation." (PMID 23730306, 2013). "Interestingly, mutations in KCNQ2 have been shown to cause benign familial neonatal convulsions (BFNC), a rare autosomal dominant inherited form of epilepsy." (PMID 23730306, 2013). "Conversely, fluorescence data from the epilepsy-associated mutation R214W shows a marked separation between the G(V) and F(V) and a faster fluorescence time course compared to the ionic current time course (brown), suggesting that R214W changes the VSD-PD coupling of KCNQ2." (PMID 35642783, 2022). "Furthermore, targeted therapy of KCNQ2-related epilepsy with an approved small molecule M-current activator (retigabine/ezogabine) has been demonstrated, but whether all disease-associated variants will respond equally to this drug has not been determined." (PMID 35104249, 2022). "We determined the functional properties of 39 additional epilepsy-associated KCNQ2 variants that had not been investigated at the time of our experiments (8 BFNE, 30 DEE, 1 unknown phenotype)." (PMID 35104249, 2022).
epilepsy (continued). "SMIT1 both alters KCNQ selectivity for BHB, and also amplifies the effects of clinically relevant concentrations of BHB on KCNQ2/3, suggesting we should consider KCNQ2/3–SMIT1 complexes when evaluating the mechanisms underlying the therapeutic action of the ketogenic diet and fasting in epilepsy." (PMID 32111967, 2020). "KCNQ1 and KCNQ4 are expressed in multiple tissues (KCNQ4 in the auditory system and vasculature, KCNQ1 in the cardiovascular system and multiple epithelia) and their activation might cause unwanted off-target effects if one were instead intending to target KCNQ2 in epilepsy, for example." (PMID 31701029, 2019). "A considerable proportion of patients with these types of epilepsies also have ID and/or behavioral problems (ADHD, ASD, anxiety, depression) which supports a common genetic etiology and accordingly suggest KCNQ3 (and KCNQ2) as candidate susceptibility genes for ID and various psychiatric disorders." (PMID 23596459, 2013). "To address this challenge, we have focused on the KV7.2 voltage-gated potassium channel gene (KCNQ2), known for its link to developmental delays and various epilepsies, including self-limited benign familial neonatal epilepsy and epileptic encephalopathy." (PMID 38474157, 2024). "Furthermore, a recent study has indicated that KCNQ2 may be linked to intellectual disability in the absence of epilepsy." (PMID 37497102, 2023). "Transdermal nicotine treatment was successfully used in a CHRNA4-related case and carbamazepine in KCNQ2 and PRRT2 epilepsy." (PMID 33726816, 2021). "KCNQ2 and SCN2A had both a concentration of EMR usage in the infantile period reflecting self-limited early onset epilepsies and a tail extending through childhood, reflecting DEE." (PMID 34031551, 2021). "It has been suggested that neonates with KCNQ2, KCNQ3 or SCN2a epilepsy respond well to treatment with low-dose sodium channel blockers, such as carbamazepine or oxcarbazepine." (PMID 33670692, 2021). "Dysregulation of the ion channel genes SCN2A, potassium voltage-gated channel subfamily Q member 2 (KCNQ2), and KCNQ3 contribute to the progression of epilepsy in infants, but more interestingly, these are known to be repressed by NRSF." (PMID 30572571, 2018). "We find current evidence for this preferential enrichment among six epilepsy genes: CDKL5 (P = 1.1 × 10−12), KCNQ2 (P = 1.1 × 10−23), PCDH19 (P = 0.003), SCN1A (P = 9.7 × 10−9), SCN2A (P = 1.9 × 10−4), and SCN8A (P = 3.5 × 10−4)." (PMID 28864458, 2017). "Considering that KCNQ2 and KCNQ3 turned out to directly contributing to the initiation and progression of epilepsy, our predicted genes ANK1 and ANK2 as the functional components of ankyrins may very probably be epilepsy associated genes, validating our prediction." (PMID 28255556, 2017). "Mutations in other genes encoding ion channels, such as KCNQ2 in benign familial neonatal seizures and SCN1A in Dravet syndrome, led to the “channelopathy” hypothesis, which postulates that dysfunction or dysregulation of ion channels is a common mechanism underlying epilepsy syndromes." (PMID 26302787, 2015). "Recent studies indicated the potential of miRNAs including miR223 as potential therapeutic targets for various diseases, such as K+-channel-related cardiovascular disorders (voltage-gated K+ channel, KV4.2/KCND2) and epilepsy (voltage-gated K+ channels, KV2.1/KCNMB1 and KV7.2/KCNQ2)." (PMID 38892210, 2024).
epilepsy (continued). "However, potassium voltage-gated channel subfamily Q member 2 (KCNQ2), SCN1A, and GABRG2 are three established genes among top ten genes for common epilepsies." (PMID 33096746, 2020). "The KCNQ2 sequencings done were selected from 131 nonconsanguineous pediatric epileptic patients (age range: 2 days to 18 years) with nonlesional epilepsy." (PMID 31199083, 2019). "Familial neonatal early-onset seizures have been considered as a clinical clue for a KCNQ2-related etiology; however, few cases with later childhood epilepsy and no neonatal seizures, as well as intellectual disability, language impairment, and sometimes autistic features, have been reported." (PMID 39796146, 2024). "For instance, the positive response of KCNQ2-epilepsies (regardless of the severity of the clinical phenotype) to SCBs may reflect the importance of choosing the treatment based on genetic diagnosis." (PMID 34679360, 2021). "However, our understanding of the cellular mechanisms that may both explain the origins of epilepsy and inform treatment strategies for KCNQ2 and KCNQ3 dysfunction is still lacking." (PMID 33863780, 2021).
Epileptic encephalopathy (70 papers, 2013 to 2026). A condition in which epileptiform abnormalities are believed to contribute to the progressive disturbance in cerebral function. "We further highlight a significant downregulation of the developmental and epileptic encephalopathy (DEE) associated gene KCNQ2 (potassium voltage‐gated channel subfamily Q member 2; avg." (PMID 40704780, 2025). "This family consists of five members, with the KCNQ2 channel most commonly linked to developmental epilepsy and epileptic encephalopathy." (PMID 40667464, 2025). "Mutations in the KCNQ2 gene cause highly diverse phenotypes ranging from normal, familial neonatal seizures to early onset developmental and epileptic encephalopathy." (PMID 38474157, 2024). "KCNQ2 mutations can cause benign familial neonatal convulsions (BFNCs), epileptic encephalopathy (EE), and mild-to-profound neurodevelopmental disabilities." (PMID 35269516, 2022). "Mutations in KCNQ2 channels cause severe neurodevelopmental disorders, including epileptic encephalopathies." (PMID 35642783, 2022). "De novo mutations in KCNQ2 also cause epileptic encephalopathy (EE), which is characterized by persistent seizures that are often drug refractory, neurodevelopmental delay, and intellectual disability." (PMID 35928789, 2022). "KCNQ2, a brain-specific voltage-gated potassium-channel subunit, has been implicated in patients with epileptic encephalopathy and neonatal‐onset seizures." (PMID 33484326, 2021). "KCNQ2 encodes a voltage-gated potassium channel that is expressed in the brain and is involved in the etiology of epileptic encephalopathy, early infantile (EIEE7, phenotype MIM# 613720), and benign familial neonatal seizures-1 (BFNS1, phenotype MIM#121200)." (PMID 33333793, 2020). "Both severe epileptic encephalopathy and self-limited epilepsies were associated with KCNQ2 and SCN2A variants." (PMID 31572294, 2019). "KCNQ2 mutations were also associated with epileptic encephalopathy, and KCNQ2 encephalopathy often manifests refractory seizures, cortical abnormalities, and severe neurodevelopmental delay." (PMID 26636052, 2015). "This nascent genotype-phenotype correlation is reminiscent of KCNQ2-associated epileptic encephalopathy, where loss-of-function mutations are associated with neonatal onset, while gain-of-function mutations are associated with infantile onset." (PMID 26933568, 2015). "Recently, de novo mutations of KCNQ2 have been described in early onset epileptic encephalopathies (EOEEs; OMIM#613720)." (PMID 23692823, 2013). "An epileptic encephalopathy similar to Ohtahara syndrome, attributable to mutations in the KCNQ2 gene that encodes the voltage-gated potassium channel Kv7.2, has been recently described." (PMID 23970964, 2013). "Additionally, there are few cases of the KCNQ2 pathogenic variants leading to the development of early epileptic encephalopathy into West syndrome." (PMID 40342533, 2025). "Interestingly, either KCNQ2 GOF or LOF (p.V175L mutation) is found to produce early-onset epileptic encephalopathy in children." (PMID 41155561, 2025). "Both CACNA1E and KCNQ2 are clinically relevant genes associated with epileptic encephalopathy." (PMID 38283851, 2024). "Over the last decade KCNQ2 channels have arisen as fundamental and indispensable regulators of neonatal brain excitability, with KCNQ2 loss-of-function pathogenic variants being increasingly identified in patients with developmental and epileptic encephalopathy." (PMID 37409016, 2023).
Epileptic encephalopathy (continued). "Kcnq2 is one of the most commonly mutated genes in developmental and epileptic encephalopathy." (PMID 38052789, 2023). "Importantly, we observed genotype-dependent differences in the response of KCNQ2 variants to retigabine, a proposed precision therapy for KCNQ2 developmental and epileptic encephalopathy." (PMID 35104249, 2022). "In human beings, pathogenic variants in the KCNQ2 gene could cause benign neonatal seizures and epileptic encephalopathy." (PMID 35557555, 2022). "Among the KCNQ family of proteins, KCNQ2 channels have received particular attention because mutations in this channel have been associated with a variety of neurodevelopmental phenotypes, including epileptic encephalopathy, and more recently, autism." (PMID 35642783, 2022). "Researchers uncovered that KCNQ2 variants leading to haploinsufficiency often relate to a milder phenotype—benign familial neonatal seizures, while variants with DN effect are inclined to a severer phenotype—epileptic encephalopathy." (PMID 35071126, 2021). "Interestingly, a loss-of-function variant of the S4–S5 Arg in human KCNQ2 (R213W) associates with both benign familial neonatal convulsions and the much more severe epileptic encephalopathy." (PMID 32655402, 2020). "Similarly, novel pharmacological agents such as NMDA receptor antagonists for GRIN2A/GRIN2B mutations, KCNQ channel openers for KCNQ2-related epileptic encephalopathies, and IGF-1 analogues for trophic deficiency syndromes signify the forthcoming generation of personalized treatments." (PMID 41470225, 2025). "Together these results suggest Phox2b-expressing neurons including those in the ventral parafacial region (putative RTN neurons) are vulnerable to Kcnq2 channelopathies and may contribute to breathing problems associated with KCNQ2 developmental and epileptic encephalopathy (DEE)." (PMID 38052789, 2023). "However, a recent line of evidence shows that some KCNQ2 mutations also cause early onset epileptic encephalopathies (EOEEs) or early infantile epileptic encephalopathies (EIEE), such as Ohtahara syndrome, which are associated with intractable seizures followed by profound psychomotor delay." (PMID 26910900, 2016). "Loss-of-function (LOF) KCNQ2 variants, particularly dominant-negative missense mutations that reduce potassium currents in Kv7.2, are typically responsible for KCNQ2-related early infantile developmental and epileptic encephalopathy." (PMID 40310132, 2025). "Enzyme replacement therapy was commenced in three individuals and six infants were diagnosed with KCNQ2-related epileptic encephalopathy, informing choice of anti-epileptic agent." (PMID 37291213, 2023). "Analysis of patient 4’s exome revealed a de novo substitution mutation in the gene KCNQ2 (c.740C>A; p.Ser247Ter; CADD PHRED score: 41), which is associated with early infantile epileptic encephalopathy." (PMID 37408271, 2023). "KCNQ2-related disorder is typically characterized as neonatal onset seizure and epileptic encephalopathy." (PMID 35557555, 2022). "A literature search of PubMed was undertaken using the key words KCNQ2 encephalopathy, KCNQ2 developmental encephalopathy, KCNQ2 seizures, KCNQ2 developmental and epileptic encephalopathy, KCNQ2 epileptic encephalopathy, KCNQ2‐EEG and KCNQ2‐DEE." (PMID 33681646, 2021). "Caused by the impaired function of potassium channels due to KCNQ2 variants, KCNQ2 encephalopathy was a clinical syndrome with a wide range from BFNS to early onset epileptic encephalopathy." (PMID 33897753, 2021). "Literature review of patients with KCNQ2 developmental and epileptic encephalopathy (KCNQ2‐DEE) reveals, based on 16 reports including 139 patients, a clinical phenotype that includes age‐ and disease‐specific stereotyped seizures." (PMID 33681646, 2021). "VEEGs of the patients with KCNQ2-related epileptic encephalopathy showed a BS pattern, hypsarrhythmia, or multifocal epileptiform activity in our study, which is similar to reported studies." (PMID 34711204, 2021).
Epileptic encephalopathy (continued). "In our study, patients with sensorineural hearing loss, seizures, epileptic encephalopathy and cardiomyopathy showed mutations in LOXHD1, KCNQ1, KCNQ2 and MYH7 genes." (PMID 33484326, 2021). "Kv7.2/Kv7.3 dysfunction resulting from KCNQ2 mutations predominantly causes self-limited or benign epilepsy in neonates, but also causes early onset epileptic encephalopathy." (PMID 26910900, 2016). "KCNQ2 and KCNQ3 gene mutations usually lead to BNFE or to more severe epileptic encephalopathies." (PMID 38003469, 2023). "Altered PIP2 sensitivity of neuronal Kv7.2 channel is involved in KCNQ2 epileptic encephalopathy." (PMID 34650221, 2021). "For example, one or more individuals who developed a therapy-resistant epileptic encephalopathy have been observed in families with BFNS1; the p.Arg213Trp KCNQ2 pathogenic variant has been reported in an individual with severe epileptic encephalopathy and in another family with normal outcome." (PMID 34711204, 2021). "KCNQ2-related EIEE should be distinguished from other early onset epileptic encephalopathies." (PMID 34833120, 2021). "These clinical features during the neonatal period were essentially nondistinguishable from those in early infantile epileptic encephalopathy due to KCNQ2 and SCN2A mutations." (PMID 31675180, 2019). "For example, if an expert knows the outcome of ES is a diagnosis of KCNQ2-related epileptic encephalopathy, the expert may exaggerate their ability to treat this patient without ES, which hinders the ability to consider any alternative diagnoses when performing judgment tasks." (PMID 37973547, 2023). "In this region, three genes including KCNQ2, EEF1A2, and CHRNA4 were related to dominant epileptic encephalopathy, and KCNQ2 is the key gene." (PMID 35557555, 2022). "It is now known that mutations in Kv genes (KCNQ1–5) are related to several disorders like long-QT syndromes (KCNQ1) and a range of neuropsychiatric disorders (KCNQ2–5), ranging from some types of neonatal epilepsy (NEE) and epileptic encephalopathies (DEEs) up to developmental disorders." (PMID 38999185, 2024).